BRAF (B-Raf proto-oncogene, serine/threonine kinase)
Diseases named in the same sentence as BRAF in open-access papers (continued):
Sharing a sentence is not in itself a finding about the gene and the disease.
tumor (continued). "Patients with BRAF-mutant tumours, asymptomatic brain metastases, or PD-L1-negative status appear to reach better survival outcomes with the combination relative to single-agent immunotherapy." (PMID 37404764, 2023). "The constitutively activated BRAF promotes tumour cell proliferation and survival but also cell invasion, metastasis, and evasion of the immune response." (PMID 37627054, 2023). "Because of the spread of the tumor to distant organs, immunotherapy is often performed in stage 4, such as BRAF and MEK inhibitors." (PMID 37191832, 2023). "Higher T cell density associated with low stage [P = 0.00025 (tumour centre), P < 0.0001 (invasive margin)], high tumour grade (P < 0.0001, P = 0.0032), MMR deficiency (both P < 0.0001) and BRAF mutation (P < 0.0001, P = 0.062)." (PMID 37002343, 2023). "The involvement of BRAF in T cell exhaustion was further supported by its inhibition and following significant reestablishment of anti-tumor T cell responses, implying the potential role of BRAF inhibitors in immune-based therapies." (PMID 38313431, 2023). "The aim of this study is to evaluate the prognostic effect of primary tumor location in the Belgian population and to determine the role of biomarker status (MMR, BRAF, and RAS mutational status) in this prognostic effect." (PMID 37071802, 2023). "Regarding STRFS, multivariate analyses showed that tumor size, ETE, BRAF mutation, MLN number, and high LNR (≥0.75) were independent influencing factors (p<0.05)." (PMID 37790606, 2023). "In the RAS wild-type cohort (n=9), 3/4 patients with BRAF Class II alterations and 1/4 patients with RET rearrangements qualified for RAI, with 3 SDs and 1 PR (in patient with a BRAF-altered tumor)." (PMID 37435488, 2023). "Different mutation profiles of RET and BRAF genes were detected in MTC and PTC mixed-tumor foci in different cases, suggesting that the two types of cancer were driven by different genes, indicating the co-occurrence of the two independent cancers." (PMID 37580706, 2023). "While different molecular mechanisms of resistance have been identified, this article examines the literature relating to autophagy, and provides an overview on the relationship between autophagy and BRAF-inhibitors in various tumor models." (PMID 37834222, 2023). "Regarding pathways related to tumor activities, only the RTK-RAS pathway was significantly affected due to BRAF mutations." (PMID 37795451, 2023). "Overcoming these challenges requires identifying the molecular mechanism underlying tumor cell resistance to BRAF and MEK inhibitors and analyzing their specificity in different BRAF tumors." (PMID 37834284, 2023). "While BRAF and KRAS mutations both lead to activation of the RAS-RAF-MEK-cascade, KRAS mutations occur during tumour progression in the classical pathway or suppressor pathway while BRAF mutations are initiating mutations in the sessile serrated pathway." (PMID 37344790, 2023). "When NRAS-mutated cells become dominant in the tumor, they can reactivate MAPK signaling, circumventing the inhibitory effects of BRAF inhibitors." (PMID 38067230, 2023). "Regarding BRAF mutational status, better survival outcomes with a nivolumab–ipilimumab regimen have been observed in patients with BRAF-mutant tumours." (PMID 37404764, 2023). "In PCPs, the expression of oncogenic BRAF V600E is observed in most of the tumor cells but the activation of the MAPK pathway is rather restricted to a few tumor cells." (PMID 36979325, 2023). "With the emergence of KRAS and BRAF mutations, resistance to EGFR-targeted therapy has developed, driven by mechanisms affecting both cellular pathways and the tumor microenvironment." (PMID 37762323, 2023).
tumor (continued). "BRAF inhibitors, such as dabrafenib, trametinib, were used for 7 patients who suffered tumor recurrence and showed clinical stability and radiographic improvement." (PMID 37448517, 2023). "With the aim to optimise patient selection criteria for LT, most of the ongoing studies include molecular tumour markers in their inclusion criteria, and exclude patients with BRAF mutant tumours or MSI." (PMID 36879000, 2023). "Inactivation of many tumor suppressor genes had strikingly different effects on the growth of BRAF-driven tumors compared to tumors driven by either KRAS variant." (PMID 37828026, 2023). "Patients with RET fusion-positive PTCs were significantly younger than patients with BRAF V600E and RAS-mutated carcinomas (P < 0.001) and had significantly larger tumor than patients with the BRAF V600E-mutated carcinomas (P < 0.001)." (PMID 37882481, 2023). "Our results confirmed the predictive role of the primary tumor site for third-line anti-EGFR-based treatment in RAS/BRAF wt patients." (PMID 36895480, 2023). "Intriguingly, systematic analysis of mutated tumor genes identified EGFR, MET, BRAF, and TERT as determinants in LUAD, and NOTCH, FGFR1, SOX2, and PI3CA as determinants in LUSC." (PMID 37046851, 2023). "The prognostic impact of those BRAF-mutant PLGGs has been modified since the tumor was entirely resected and then reached the prognosis of BRAF-fused tumors." (PMID 36831610, 2023). "This allows for comprehensive therapy recommendations such as concomitant HER2/MET-amplifications as a potential primary resistance mechanism and MET and BRAF fusions that cannot be as easily assessed in the thoracic tumour board." (PMID 36572733, 2023). "Thirdly, specific details regarding tumor pathology, such as microsatellite stability, BRAF, and K-RAS, were unavailable in the SEER database." (PMID 37245170, 2023). "CRCs harboring KRAS and BRAF mutations are often refractory to chemotherapy, resulting in a poorer prognosis than cases involving wild-type KRAS and BRAF due to tumor recurrence and metastasis." (PMID 37972012, 2023). "The text essentially asserts the relations among the entities: BRAF V600E, tumor, trametinib, and dabrafenib." (PMID 37502629, 2023). "Comprehensive molecular profiling by NGS of the tumor progressing on BRAF/MEK inhibitors showed the appearance of a KRAS G12C mutation, which is typically mutually exclusive with BRAF mutations in LG-SCs." (PMID 36967525, 2023). "The mutation incidence in tumor samples was as follows: NF2 R57* (15/27), PIK3CA E545K (13/27), BRAF Hotspot mutations (10/27), SMO L412F (9/27), SMO W535L (7/27), with varying mutant allele frequencies represented by the dot sizes." (PMID 38259646, 2023). "Based on this limited evidence, we retrospectively compared the efficacy of third-line therapy with anti-EGFR-based treatment versus R/T in RAS/BRAF wt mCRC patients, according to the primary tumor site." (PMID 36895480, 2023). "In the same way, the identification of a BRAF-specific NF-κB signature for tumor progression will enable to determine biomarkers that aid in prognosis and in the evaluation of treatment efficacy." (PMID 37973791, 2023). "Tumor regression was also achieved by combining BRAF inhibitor BGB659 with EGFR inhibitor cetuximab in RAS - amplified, vemurafenib - resistant models." (PMID 37920169, 2023). "TGF-β produced by a hyperactivated tumor stroma has been proposed to skew the BRAF-mutant serrated precursors from the high-immune-infiltration subtype to the mesenchymal subtype with poor prognosis." (PMID 37219625, 2023). "Regarding BRAF gene, one tumour harboured V600E via local assessment, in contrast to NGS result; samples used for both procedures were from different origin." (PMID 37097008, 2023). "For patients with RAS/BRAF wild-type tumours, the use of an anti-EGFR agent with FOLFOX or FOLFIRI is an accepted policy in left-side primary tumours with CRCLM." (PMID 36674640, 2023).
tumor (continued). "In KRAS‐mutated tumors, BRAF inhibitors promote heterodimerization of BRAF and CRAF, thereby activating the MAPK pathway and helping secondary tumor development." (PMID 37250144, 2023). "Three genes (ARTX, BRAF, and MGMT) contained mutations with a moderate or high impact on protein functions in the original tumor or PDX sample." (PMID 38001935, 2023). "For example, differences in APC, BRAF, KRAS, and NRAS are associated with the location of the primary tumor, whereby mutations in KRAS and BRAF seem to result in worse overall survival and the recurrence site in patients with PM." (PMID 37629011, 2023). "By increasing the internalization of siRNA in ATC cells, the nanoparticles reduced BRAF expression to suppress tumor cell survival and decrease micrometastases." (PMID 37833748, 2023). "BRAF alterations, missense mutations or aberrant fusions, as well as other MAPK alterations, are seen in numerous glioneuronal tumours." (PMID 36831464, 2023). "A combination regimen consisting of BRAF inhibitors—dabrafenib plus trametinib—was approved by the FDA for ATC-positive BRAFV600E mutation and resulted in significant tumor volume regression and 100% control of the locoregional spread." (PMID 38115146, 2023). "In BRAF mutant melanoma cells, PTEN loss negatively affects anti-tumor immunity and T cell tumor recruitment." (PMID 36909198, 2023). "We found that 2 miRNAs by targeting 2 metastasis-related mRNAs were correlated with tumor-infiltrating macrophages, HRAS, and BRAF gene mutation status." (PMID 38036953, 2023). "In all four xenograft models, triplet combinations resulted in statistically significantly improved tumor growth inhibition as compared to BRAF + EGFR or BRAF + SRC inhibitor doublets." (PMID 36759733, 2023). "This additional activation of the Pi3K/AKT/mTOR signaling pathway seems to exacerbate the cooperation with BRAF activation and the promotion of tumor cell proliferation." (PMID 36831610, 2023). "Anti-PD-1 therapy combined with MEK inhibition produced lasting tumor regression in CT26-innoculated BALB/c mice and the triple therapy with trametinib (MEK inhibitor), dabrafenib (BRAF inhibitor) and anti-PD-1 showed a strong anti-tumor effect." (PMID 37345111, 2023). "In this study, combined YAP inhibition with RAF or MEK inhibition induced synthetic lethality not only in BRAF tumor cells but also in RAS tumor cells." (PMID 37834284, 2023). "Grouping BRAF mutations into BRAFV600E and BRAFnon-V600E and their analysis according to specific tumor localizations showed that all four BRAFnon-V600E mutations originated in the rectum." (PMID 37886935, 2023). "Current therapies based on MEK, BRAF and CDK4/6 inhibitors tend to induce resistance by activating OXPHOS and fatty acid oxidation, thus reducing the tumour mass but increasing the risk of relapse." (PMID 37495601, 2023). "Very few coincident tumor suppressor alterations have been investigated in the context of oncogenic BRAF-driven autochthonous lung tumors, and the extent to which tumor suppressor effects differ in EGFR-driven tumors remains poorly understood 36,41–44." (PMID 37828026, 2023). "A synergistic effect between TERTp and BRAF V600E or RAS mutations has been well-documented by several studies and has been shown to promote tumour aggressiveness and negatively impact disease-free survival." (PMID 37374164, 2023). "Subjects with the BRAF V600E mutation had significantly more frequent occult metastases (p = 0.008), classic PTC variant (p < 0.001), significantly smaller tumor sizes (p = 0.021), and a higher rate of CPSF2 3+ expression (p = 0.049)." (PMID 36672561, 2022). "Studies conducted on mice showed a tumor regression after dual blockade of BRAF and EGFR using vemurafenib and cetuximab." (PMID 36556139, 2022).
tumor (continued). "BRAF-MT CRC has more stromal cells, more immune cell infiltration, and lower tumor purity in a recent study that evaluated the immune microenvironment of BRAF-MT CRC using The Cancer Genome Atlas and Gene Expression Omnibus data." (PMID 35625987, 2022). "In this current work, we applied the expression data of BRAF mutated SKCM cohorts and ESTIMATE algorithm to extract a list of tumor microenvironment associated genes." (PMID 36531226, 2022). "In BRAF or RAS mutant tumor cells, DUSP4, DUSP6, SPRY2, and SPRY4 tend to be highly expressed, allowing tumors to evade regular MAPK signaling pathway feedback." (PMID 36437939, 2022). "In contrast, a multicenter study in Japan of patients with BRAF V600E mutated CRLM showed that they were prone to early recurrence and had a very low survival rate after tumor recurrence after hepatic metastasectomy." (PMID 36077604, 2022). "Here we utilize cell and murine models to demonstrate that oncogenic BRAF leads to activation of the Hippo tumor suppressor pathway, both in melanocytes in vitro and nevus melanocytes in vivo." (PMID 35768444, 2022). "The current strategy for LS screening in Switzerland involves two tumour-based tests (IHC and BRAF V600) followed by DNA sequencing." (PMID 34782441, 2022). "This tumour type is characterised by a high frequency of genetic mutations within the RAS-RAF-MEK-ERK pathway, with mutations in BRAF, NRAS and NF1 as the main drivers of transformation." (PMID 36038253, 2022). "Image-guided computational pharmacology identified strategies to overcome poor tumor penetration of BRAF-targeted therapies." (PMID 35486732, 2022). "Determination of primary tumor location, MMR status and RAS/BRAF mutational status is mandatory to assess the optimal therapeutic strategy in the first-line setting." (PMID 36230751, 2022). "For example, the MSI-high phenotype and somatic BRAF V600E mutation are strongly correlated with both diet and CRC survival; thus, it is important to adjust for these tumor phenotypes." (PMID 35954465, 2022). "The targeted therapies are tailored to the patient based on the specific genetic background of the tumor (e.g., mutation or altered expression of EGFR, KRAS, BRAF, PIK3CA, PTEN, HER2, or gene fusion of ALK, ROS1, RET)." (PMID 35205667, 2022). "CMS 1 tumours are characterised by high immune infiltration and are commonly MSI, BRAF-mutated and right-sided, which is in line with the current findings." (PMID 36497419, 2022). "Various international trials have also found BRAF mutations in CRC present early in disease progression (stage I/II) and occur mainly in right-sided tumours, females, and those over the age of fifty at diagnosis." (PMID 34877621, 2022). "Treatment with hypolipidemic agents or an inhibitory homolog of acetoacetate attenuated the BRAF V600E tumor growth." (PMID 35681673, 2022). "BRAF mutation will continuously activate the downstream MEK-ERK signal pathway and play a vital role in tumor growth, proliferation, invasion, and metastasis." (PMID 36380085, 2022). "Tumour testing used IHC for MMR proteins with targeted BRAF and MLH1 promotor methylation testing followed by germline mutation and somatic testing as appropriate." (PMID 33452216, 2022). "Cell viability and metastasis-related processes were attenuated by DEL-22379 treatment, but mostly in BRAF-mutant cells, whereas in vivo tumor growth and dissemination were strongly reduced for BRAF-mutant cells and mildly reduced for RAS-mutant cells." (PMID 36056964, 2022). "Tumor cells resistant to BRAF inhibitors or MEK inhibitors can be sensitized by treatment with SCH772984." (PMID 36233210, 2022).
tumor (continued). "BRAF/MEK-inhibitors can be initiated to induce rapid tumor response and provide symptom relief and to create the opportunity to commence other treatments, including immune checkpoint inhibitors, at a later time point." (PMID 35247992, 2022). "Tumor progression upon 2L treatment required the re-initiation of either BRAF ± MEKi or CPI as the third- or fourth-line therapy in 62 patients." (PMID 35565212, 2022). "In summary, our findings uncover a critical role for BRAF/TBX3/CXCLs signaling in the regulation of anti-tumor immunity and suggest the use of combination CXCR2 inhibitor with MAPKi therapy in patients with advanced PTC." (PMID 35332119, 2022). "Regorafenib, a multi-kinase inhibitor, inhibits several numbers of protein kinases implicated in tumour growth (KIT, RET, RAF-1, and BRAF p38 MAP kinase), metastasis (PDGFR- and FGFR1), and tumour angiogenesis (VEGFR-1, -2, and -3)." (PMID 36614133, 2022). "Two hallmark features defining cutaneous melanomas are the constitutive activation of the MAPK intracellular cascade, through mutually exclusive gain-of-function mutations in BRAF and NRAS and the high tumor mutational burden (TMB)." (PMID 35409020, 2022). "This analysis evaluates the relevance of primary tumor location (PTL) in RAS/BRAF wild-type mCRC patients, when dividing the colorectal frame into six segments." (PMID 35158793, 2022). "Here, we identified AK2 as an AMP-sensing negative regulator of BRAF and delineated the tumor suppressive role of AK2 in liver tumorigenesis of HRASG12V-transgenic (Tg) mice." (PMID 35585049, 2022). "Among these 38 patients, 13 achieved a renewed tumor response (34.2%), with 3 patients even showing a complete response to BRAF ± MEKi rechallenge, which was ongoing in two patients at the time of data-lock." (PMID 35565212, 2022). "The addition of vemurafenib to irinotecan and cetuximab improved progression-free survival (PFS) and tumor response in BRAF-MT CRC that was previously treated with one or two regimens of palliative chemotherapy in another prospective randomized phase II study." (PMID 35625987, 2022). "Each patient’s sex, age, genetic mutation status (BRAF, NRAS, KRAS), and MSI status based on tumor genetic profiling; location of the primary tumor; site of metastasis; and time from diagnosis to death were collected from the hospital information system." (PMID 36136880, 2022). "Specifically, mutations in the BRAF gene result in the continuous downstream activation of MEK/ERK/MAPK pathways, which affects tumor cell differentiation, migration, and proliferation." (PMID 36077604, 2022). "Baseline upregulation of several RTKs, RAS, p-CRAF and p-p90rsk were also seen in three BRAFV600E HGG tumours (including one paediatric and one adolescent sample) collected following relapse after BRAF inhibitor treatment." (PMID 36582791, 2022). "Some clinical factors, including age, TNM stage, tumour markers (CEA and CA19-9), and genetic mutations (KRAS, NRAS, and BRAF), have been reported as risk factors for colorectal metastasis in previous studies." (PMID 35296011, 2022).